INS (insulin)
Diseases named in the same sentence as INS in open-access papers (continued):
Sharing a sentence is not in itself a finding about the gene and the disease.
diabetes (continued). "In our systematic review and meta-analysis, 21 cohort studies were included and seven independent risk factors were screened out, including age of diabetic onset, duration of diabetes, HbA1c, hypertension, eGFR, high albuminuria and antidiabetic therapies (insulin and oral drugs)." (PMID 39391902, 2024). "Insulin pumps, continuous glucose monitoring, and automated insulin delivery systems: The development of modern delivery systems combined with real-time glucose monitoring has significantly advanced diabetes care." (PMID 39766270, 2024). "Despite being on multiple daily injections (MDI) of insulin with a total daily dose exceeding 200 units, his diabetes remained uncontrolled, leading to complications that included nephropathy, proliferative diabetic retinopathy, peripheral neuropathy, and erectile dysfunction." (PMID 39108603, 2024). "Interestingly, diabetes-related pathways regulation of insulin secretion (R-HSA-422356), and integration of energy metabolism (R-HSA-163685), as well as puberty-related gonadotropin-releasing hormone receptor pathway (P06664), were enriched." (PMID 38775154, 2024). "Recent studies have reported that circRNA might play a crucial role in blood glucose level regulation, influencing insulin secretion and islet Beta- cell proliferation, which are pivotal in the pathogenesis of diabetes." (PMID 39000149, 2024). "Risk factors for diabetes and prediabetes 6–12 weeks after delivery include: GDM before 24 weeks of gestation, degree of hyperglycaemia at diagnosis, insulin requirement, HbA1c in the month preceding delivery, age >36 years, family history of diabetes, preterm delivery." (PMID 39442072, 2024). "Although chronic elevated IL-1β levels contribute to islet inflammation and β-cell apoptosis, and islet expression of IL-1β correlates with diabetes development, short-term production of small amounts of IL-1β by peritoneal macrophages also contributes to enhanced postprandial insulin secretion." (PMID 38346191, 2024). "CircRNA containing the lariat sequence of intron 2 in insulin gene is reported to modulate insulin production in T2D patients and diabetes rodent models, which may clarify the impairment of secretion ability." (PMID 39239069, 2024). "Diabetes status did not change other associations between brain insulin signaling measures and cognition." (PMID 38029396, 2024). "After pancreatic surgery, endocrine insufficiency may also occur due to a reduction in insulin production by pancreatic β-cells, resulting in pancreatogenic diabetes (type IIIC diabetes)." (PMID 38892509, 2024). "Insulin requirements must be assessed in patients with long-term type 2 diabetes mellitus." (PMID 38654804, 2024). "It is important to note that since CETP and SGLT2 inhibitors are both oral drugs, their combination therapy represents an oral therapeutic strategy for treatment-resistant diabetes prior to use of injectable drugs such as insulin or glucagon-like peptide 1 (GLP1) receptor agonists." (PMID 38962682, 2024). "Conversely, the reduction in muscle mass and strength leads to decreased energy expenditure, contributing to the promotion of adiposity and obesity, and in turn, obesity perpetuates a vicious cycle by increasing insulin resistance, thereby expediting the onset and progression of diabetes." (PMID 38612998, 2024). "A more recent study in a mouse model showed that P4 can cause increased hepatic glucose production via gluconeogenesis under the limited or impaired action of insulin, which may exacerbate hyperglycemia in diabetes where insulin action is limited." (PMID 38539988, 2024). "Notably this gene encodes a calcium channel complex that enables influx of Ca2+ and when defective leads to impaired islet insulin secretion and diabetes." (PMID 39687022, 2024). "Furthermore, insulin therapy cannot reverse β-cell damage and progress of diabetes, or replicate the normal physiological state." (PMID 38681772, 2024).
diabetes (continued). "The essential features of the 1-year and 3-year follow-up models were baseline eGFR, BUN, creatinine, triglyceride, age, gender, Hgb, CHOL, PLTs, albuminuria, diabetes disease, hypertension and related medications (eg, diuretics, insulin, dipeptidyl peptidase-4 and calcium channel blockers)." (PMID 38677774, 2024). "Diabetes duration (years) (OR = 1.02; [95% CI: 1.01–1.03] p = 0.001), HbA1c at baseline (OR 1.27; [95% CI: 1.10–1.46] p = 0.001), and insulin requirements (units/kg body weight) (OR = 13.99; 95% [CI: 5.63–34.77] p < 0.001) were also factors favoring poor control." (PMID 38273326, 2024). "Given that a meta-analysis has shown a significant positive association between diabetes and RCC incidence, improved insulin sensitivity through alcohol consumption could serve as an indirect protective factor against RCC." (PMID 38957811, 2024). "The resolution of antagonisms on insulin action may induce diabetes remission and allow insulin therapy interruption." (PMID 38539988, 2024). "Current results confirm that irisin plays a multi-dimensional protective role in diabetes by reducing insulin resistance, promoting β cell proliferation, increasing insulin secretion, improving glucose uptake in peripheral tissues, and regulating gluconeogenesis." (PMID 38405155, 2024). "TRPM5 participates in carbohydrate metabolism and glucose homeostasis regulation by regulating the taste response and insulin secretion, which may play a role in controlling calorie intake and preventing diabetes." (PMID 38255767, 2024). "Future therapeutic strategies may target these molecules and develop new drugs to enhance the efficacy of the insulin signaling pathway to manage diabetes more effectively." (PMID 39596859, 2024). "A randomized, versus placebo study in subjects with insulin-treated diabetes mellitus and EPI showed that PERT could be used safely, and reduced the frequency of mild and moderate hypoglycemia." (PMID 38331895, 2024). "In line with our results, another randomized controlled clinical trial reported that 1,000 μg CrPic daily intake for 24 weeks resulted in an increase in blood Cr level as well as a significant reduction in hepatic lipid deposition among type 2 diabetes mellitus (T2DM) insulin sensitivity responders." (PMID 38721033, 2024). "Despite observing some men with an impaired response in insulin sensitivity in our study, they improved their muscle strength, which is also an important factor for health and longevity, such as for lower future cancer mortality and diabetes." (PMID 38921470, 2024). "In tests performed in animal species, the consumption of fruits rich in vitamin C helped protect the body against cardiovascular disorders, gastrointestinal disorders, cancer, skin infections, and diabetes through reduced insulin glycation and an increase in glucose homeostasis." (PMID 38254523, 2024). "Additionally, exercise-induced increases in adiponectin levels, which can enhance insulin sensitivity, underscore the potential benefits of resistance training for managing diabetes-related metabolic health." (PMID 39650570, 2024). "The third group included diabetes-related terms (“a1c,” “insulin”), diet-related terms (“ketogenic,” “calories,” “binge eating”), and miscellaneous terms ranging from topics such as polycystic ovarian syndrome (PCOS), testosterone, television commercials, and reality television." (PMID 39372460, 2024). "Furthermore, the quality of new bone and osseointegration were significantly reduced, even though insulin-controlled model rats for diabetes." (PMID 38286943, 2024). "In addition, it improves insulin sensitivity and regulates diabetes-related complications such as dyslipidaemia by reducing low-density lipids, cholesterol, and triglycerides." (PMID 38313913, 2024). "However, in patients with diabetes, due to insufficient insulin secretion or insulin resistance, glucose cannot be effectively used, and the energy source of the heart turns to fatty acid oxidation (FAO)." (PMID 39045049, 2024).
diabetes (continued). "Of the total participants (mean diabetes duration = 6.6±6.2 years), 36.5% had diabetes for more than the median duration of 6 years, 80.7% were receiving insulin or insulin combined with tablets (insulin group) and the remaining 19.3% were on tablet only and/or diet control (non-insulin group)." (PMID 39587498, 2024). "Additionally, in obesity and diabetes, insulin action as an anorexigenic hormone in the hypothalamus is suppressed through insulin resistance." (PMID 38921683, 2024). "A review highlighted that poorer cognitive performance in T2DM patients over 55 years old correlated with factors such as limited diabetes knowledge, reduced frequency of self-care activities, and difficulties in managing insulin doses and adhering to medications." (PMID 38467963, 2024). "Type 2 diabetes mellitus (T2DM) is characterized by low insulin production or resistance." (PMID 39479098, 2024). "The EQUIPD study is an efficient cluster randomised trial of a quality improvement collaborative (QIC) aligned to the National Diabetes Audit that seeks to enhance the improvement capabilities of feedback recipients to increase the uptake of insulin pumps in line with NICE guidance." (PMID 38504346, 2024). "Therefore, a thorough understanding of the molecular mechanisms of insulin signaling transduction is helpful in revealing the pathogenesis of diabetes and providing new targets and strategies for the treatment and prevention of related diseases." (PMID 39045049, 2024). "The fact that statins generate diabetes was further corroborated by higher levels of blood insulin and free fatty acids (FFA), two hyperinsulinemia indices linked to insulin resistance, indicating that short‐term statin therapy could lead to pre‐diabetes." (PMID 38970167, 2024). "Finally, we used a putative subset with missing insulin-related variables to test the predictive performance of the validation cohort, consistency of subtypes over time and prediction ability of diabetes complications." (PMID 39168869, 2024). "The use of insulin is indicative of poorly controlled diabetes." (PMID 38389641, 2024). "Although this implies that the diabetes nurse may be less involved in insulin titration than in insulin initiation, we must keep in mind that the power may be too small for the secondary outcome analyses to draw firm conclusions." (PMID 38116986, 2024). "This may explain our patient's good glycemic control even after treatment switch from insulin to sulphonylurea treatment given her relatively shorter diabetes duration, low BMI, and residual endogenous insulin secretion." (PMID 39420387, 2024). "Given these constraints, a key metric for success in this trial is the ULCIP’s ability to deliver the insulin dosage as prescribed by the diabetes clinician and indicated by observed changes in patients’ blood values aligning with the expected outcomes of the insulin delivery." (PMID 39090697, 2024). "Despite advances in diabetes management, many people with diabetes still lack access to insulin." (PMID 39464844, 2024). "Diabetes is a metabolic disease characterized by hyperglycemia that derives from reduced insulin production by pancreatic islet cells or the body’s insensitivity to insulin." (PMID 39684868, 2024). "Additionally, its ability to improve glucose metabolism and insulin tolerance further highlights silymarin’s potential in managing comorbid conditions, such as diabetes, which is prevalent among obese stroke patients." (PMID 39624169, 2024). "The increased systemic apelin concentrations in diabetes and obesity may be explained by its compensation for the reduced insulin sensitivity in T2DM." (PMID 39189510, 2024). "Interestingly, the phenotype is shared with certain HNF4A (MODY1) and HNF1A (MODY4) mutations that cause hyperinsulinaemia at birth before evolving to decreased insulin secretion and diabetes in later life." (PMID 38366195, 2024).
diabetes (continued). "Impaired insulin secretion was previously linked to excessive β-cell death in diabetes and an imbalance between efficient mature insulin granule formation with a compensatory accumulation of non-functional immature insulin granules." (PMID 38744890, 2024). "Because of the nature of the mutation our patient carried it was possible to manage her diabetes with glibenclamide and oral semaglutide rather than insulin injection, a significant advantage to the patient." (PMID 38366195, 2024). "Other studies have also shown that families of insulin pump-treated children did not have lower FoH, although pump therapy has been reported to be associated with lower overall diabetes-related stress in parents of pediatric patients." (PMID 38607611, 2024). "However, considering the short duration of diabetes, milder hyperglycemia, and the presence of insulin-counter-regulatory hormones in GDM, intact HA is expected in this population." (PMID 40071056, 2024). "The reasons are unclear, but it is tempting to speculate that women treated with metformin may have milder diabetes than those on insulin therapy." (PMID 37798604, 2024). "Nonetheless, several studies have reported that PCSK9 LOF variants do not alter fasting blood glucose or insulin levels and are not linked to diabetes development." (PMID 39139638, 2024). "One participant spoke about the impact that his diabetes could potentially have on his ability to work if he was to take his insulin." (PMID 38751247, 2024). "In spite of this, in all participants without DM only recreational activity was associated with lower insulin levels in those without diabetes mellitus after controlling for confounding variables.[Model 2, β value 95% CI =-0.005 (-0.008, -0.002)]." (PMID 39469577, 2024). "Over the years, there has been a surge of interest in the possible use of dietary phenolic compounds, including flavonoids, coumarins, quinones, stilbenes, and curcuminoids, in diabetes management as they have been shown to increase insulin secretion and regulate blood sugar." (PMID 38726403, 2024). "The strengths of this study included an interventional study design and relatively long-term follow-up, a large sample size, and well-characterized metabolic phenotypes of obese populations of both MHO and MUHO subjects (since most of the studies focus on diabetes or insulin-resistant populations)." (PMID 38539836, 2024). "DM is mainly divided into: Type 2 Diabetes Mellitus (T2DM), one of the most common metabolic disorders, and it is caused by defective insulin secretion and/or inability of insulin-sensitive tissues to respond; or T1DM, an autoimmune disorder, where insulin-producing β cells are destroyed." (PMID 39476053, 2024). "The diabetes knowledge level is influenced by household disposable income per capita, occupational status, gender, age, ethnicity, family history of diabetes, insulin use, glycated hemoglobin, education level, number of complications, and health information-seeking behavior." (PMID 38751583, 2024). "Diabetes, a chronic metabolic disease that affects an individual's physical, social, and mental well-being, leads to chronic hyperglycemia because of impaired response to insulin and/or impaired insulin secretion." (PMID 39295999, 2024). "For the diabetes duration, 12 reports worked with the new-onset disease within a few days or months of diagnosis to observe the preservation of pancreatic function, glycemic control, insulin, initial symptoms, or immune response." (PMID 39194033, 2024). "Of note, IGF-1 inhibition might be contraindicated in patients with diabetes as IGF-1 enhances insulin sensitivity by promoting glucose uptake and utilization." (PMID 39759002, 2024). "Diabetes mellitus type 2 results from reduced insulin secretion resulting in hyperglycemia." (PMID 39055230, 2024). "Both type 1 and type 2 diabetes mellitus (DM) ultimately lead to abnormal insulin signaling." (PMID 38534454, 2024).
diabetes (continued). "Regarding current symptomatic treatment of diabetes, FMT is anticipated to address the root cause of diabetes by adjusting the intestinal microecological balance and improving insulin resistance, implicating multiple mechanisms such as inflammation and metabolism." (PMID 38660489, 2024). "The safety and efficacy data of virtual insulin pump initiation will enable children living in remote parts of the country, where access to pediatric endocrinology clinics is limited, to access diabetes technology to ensure optimal diabetes care." (PMID 38745900, 2024). "Lipohypertrophy is a common complication in patients with diabetes receiving insulin therapy." (PMID 38215209, 2024). "However, people with diabetes seem dissatisfied with complex and troublesome insulin injection methods, such as IMI." (PMID 39765957, 2024). "Third, detailed information regarding preconception chronic diseases, weight gain during pregnancy, and other important confounding variables, such as daily insulin dosage and economic factors (health insurance, proportion of diabetes cost to total income) were all controlled in the current study." (PMID 38664886, 2024). "Also, future studies among first degree relatives of diabetics can be conducted to identify pre-clinical diabetes, allows for less diabetic keto-acidosis, early initiation of insulin therapy, and the potential to delay or prevent diabetes onset." (PMID 38952492, 2024). "In addition, smokers with T2DM have higher glycated hemoglobin (HbA1c) levels, are more likely to experience severe hypoglycemia, and have difficulties with insulin dose adjustment and diabetes control." (PMID 39200346, 2024). "This impairment directly affects insulin secretion and contributes to diabetes progression." (PMID 39469571, 2024). "The evidence supports the idea that Se plays a vital role in insulin mimicry and anti-diabetes." (PMID 39729004, 2024). "This may contribute to challenges with diabetes management (eg, insulin rationing) and increases in diabetes-related complications." (PMID 39208386, 2024). "Collaboration across disciplines offers hope that refined individualized therapies may eventually achieve durable insulin independence through functional pancreatic cell or tissue engraftment, not only for diabetes but also for chronic pancreatitis." (PMID 38720379, 2024). "Very young children with T1D present unique diabetes management challenges for caregivers due to unpredictable food intake and physical activity, difficulties communicating symptoms of hypoglycemia, as well as high variation in day-to-day insulin requirements." (PMID 39390689, 2024). "The findings underscore the significant role of immune response processes during EV infection, suggesting that regulation of insulin and glucose might be related to diabetes mellitus (DM), specifically type 1 DM." (PMID 39234544, 2024). "In addition, we have found that the treatment of diabetic animals with sarpogrelate or insulin attenuated diabetes-induced changes in SL activities." (PMID 39057635, 2024). "Sixth, we did not subgroup the patients to ascertain whether patients who were insulin dependent had worse results when compared to those whose diabetes was managed with diet or oral hypoglycemic agents." (PMID 39192939, 2024). "These include improving oxidative phosphorylation, treating with insulin or other diabetes drugs that increase insulin sensitivity, as well as small molecules that correct mitochondrial dysfunction, ketone-based interventions, RNA therapeutics and multimodal lifestyle changes." (PMID 39238036, 2024). "The elevated plasma glucose in the case of diabetes might subsidize further disease advancement through glucotoxic effects on pancreatic β-cells and insulin sensitivity." (PMID 38672494, 2024).